MTOR (mechanistic target of rapamycin kinase)
Diseases named in the same sentence as MTOR in open-access papers (continued):
Sharing a sentence is not in itself a finding about the gene and the disease.
cancer (continued). "PRR can be involved in PI3K/AKT/mTOR, MAPK/ERK, and Wnt/β-catenin pathways, thus it can play a role in different pathological and physiological conditions, such as cancer." (PMID 37891636, 2023). "DHA exerts its anticancer effects in other cancer types, such as GBM and cervical cancer, by the induction of autophagy through mTOR inactivation." (PMID 37190124, 2023). "As a major member of dual PI3K/mTOR inhibitors, NVP-BEZ235 has undergone Phase I/II trials for the treatment of some cancers: prostate, breast, pancreatic, renal, or malignant solid tumor." (PMID 37097377, 2023). "Post-RFA treatment, elevated levels of HSP-70 expression were found in residual cancer cells, leading to their growth via the AKT-mammalian target of rapamycin (mTOR) signaling pathway." (PMID 36766643, 2023). "Apigenin has been reported to target multiple signaling pathways, such as PI3K/Akt/mTOR, MAPK/ERK, JAK/STAT, NF-kB, and Wnt/β-catenin pathways, involved in the development and progression of cancer." (PMID 38203418, 2023). "As mentioned, potential stimulators of autophagy in normal and cancer cells include SIRT1, which affects the regulation of the mTOR pathway." (PMID 36835075, 2023). "As is well known, mTOR is an important downstream protein kinase of the PI3K-Akt signaling pathway and is an influential target for cancer treatment." (PMID 37324188, 2023). "Among them, the metabolism-related pathways, such as PPAR, mTOR, VEGF, and arachidonic acid signaling pathways, appeared multiple times in various cancers." (PMID 37033970, 2023). "The growth inhibition of cancer cell lines treated with MAPK kinase (MEK) and mTOR inhibitor was greater than 60%." (PMID 37853445, 2023). "Primary cilia mediate cancer-related signaling such as the Sonic hedgehog, Wingless/INT (Wnt), NOTCH, platelet-derived growth factor (PDGF), mammalian target of rapamycin (mTOR), and Hippo pathways." (PMID 37006607, 2023). "Major pathways include pathways in cancer, PI3K-Akt pathway, TNF pathway, apoptosis pathway, mTOR pathway, etc." (PMID 38065884, 2023). "Many studies have demonstrated that some signaling pathways, such as the PI3K/AKT/mTOR pathway, RTK/RAS pathway, and SREBP2 pathway, regulate cholesterol synthesis in cancer cells." (PMID 37434430, 2023). "mTOR activation is a common feature of both primary and metastatic GEP-NENs suggesting that it is involved in cancer development and progression." (PMID 36980746, 2023). "Clinical data indicate that in over 30% of malignant tumors, the PI3K/Akt/mTOR signaling pathway is aberrantly activated." (PMID 37999532, 2023). "Depending on the mechanisms of drug-resistance in cancer cells, the protection of normal cells can be achieved with inhibitors of CDK4/6, caspases, Mdm2, mTOR, and mitogenic kinases." (PMID 36913303, 2023). "In search of the functional importance of PTEN during cancer, it is observed that PTEN act as the negative regulator of PI3K/Akt/mTOR signaling." (PMID 37602330, 2023).
cancer (continued). "Several miRNAs regulate apoptosis in cancer cells with the involvement of MTORC1, which composed of mTOR, RPTOR, MLST8, and AKT1S1." (PMID 36835100, 2023). "In terms of anti-cancer therapies, agents targeting the PIK3/mTOR/AKT pathway have been studied, due to its importance in oncogenesis across tumor types including BTC." (PMID 37046766, 2023). "Inappropriate activation of mTOR has been reported in RCC and in a variety of other cancers as well." (PMID 38273861, 2023). "Differential miRNAs target genes regulate genes involved in cancer and PI3K/Akt, MAPK, Rap1, and mTOR signaling pathways." (PMID 36791156, 2023). "The results showed that the important pathways such as the purine metabolism, pyrimidine metabolism, central carbon metabolism in cancer, ABC transporters, and mTOR signaling pathway changed significantly." (PMID 37274109, 2023). "In short, the use of KEGG pathway enrichment analysis demonstrated that the largest number of proteins was involved in cancer, PI3K–Akt, mTOR, and other signaling pathways." (PMID 36644579, 2023). "A variety of short interfering RNAs (siRNAs), as well as miRNAs have been tested for anti-cancer effects in HCC cells in vitro, targeting the major components of the EGFR/PI3K/AKT/mTOR signaling pathway." (PMID 37631344, 2023). "The mechanistic target of the rapamycin (mTOR) signaling pathway is complexly interwind with the PI3K/AKT pathway and plays a role in cell growth and survival and as a target in cancer." (PMID 38248653, 2023). "To test this possibility, in cells treated as above, we analyzed the three major pathways active in cancer cells: RAS/ERK, AKT/mTOR, and Wnt/β-catenin." (PMID 37627542, 2023). "Genes targeted by the miRNAs were found to be significantly enriched in erythropoiesis, cell cycle regulation, mTOR signalling, JAK-STAT pathway and cancer pathways." (PMID 36611033, 2023). "The top 10 enriched KEGG pathways included mTOR signaling, FoxO signaling, AMPK signaling, the longevity regulating pathway, PI3K-Akt signaling, the transcriptional misregulation pathway in cancer, and several cancer pathways." (PMID 37823029, 2023). "Quercetin stimulated autophagy in part by inhibiting the AKT/mammalian target of the rapamycin (mTOR) pathway and activating the mitogen-activated protein kinase (MAPK) pathways (involved in cancer progression and the regulation of cellular processes)." (PMID 37371941, 2023). "The miRNAs that were differentially expressed between the groups with the high and low RMscore were highly enriched in several signaling pathways related to cancer, such as TGF‐β, mTOR, PI3K‐Akt, AMPK, and Wnt signaling pathways." (PMID 35635121, 2023). "By upregulating AMPK, which inhibits the mTOR pathway, MET has been shown to promote autophagy and cell death in a variety of cancer cells." (PMID 37893061, 2023). "We found that a number of signaling networks and their components such as PI3K/Akt/mTOR, MMP‐2 and 9, Wnt/‐catenin, PARP, MAPK, NF‐κB, Caspase‐3/8/9, Bax, Bcl2, Smad4, Notch1, STAT3, Nrf2, and ROS signaling can be regulated in cancer cells by phytochemicals." (PMID 37132286, 2023). "The 1st persistent T2D disease module is enriched with the mTOR, FoxO, AMPK, and PI3K-Akt signaling pathways; longevity regulating pathway; and cancer pathways." (PMID 37823029, 2023). "Diosgenin as a spirostanol saponin found in Trigonella foenum graecum (Fabaceae) showed prominent anti-cancer activities with different mechanisms, including downregulating PI3K/Akt/mTOR gene expression." (PMID 36984763, 2023).
cancer (continued). "Cancer cells can also activate SREBP and support their increased lipid requirements for growth through an mTOR-independent mechanism." (PMID 36969840, 2023). "The HE results verified the cancer tissue and normal tissue structure in mouse livers, and the IHC results showed that the phosphorylation of ERK, mTOR and S6 was markedly increased in KLC tumors compared with KC or LC tumors." (PMID 38124228, 2023). "We also demonstrate that MEN1611 has a cytostatic effect in vivo in xenograft NSCLC tumors in immunodeficient mice and impairs cancer cell growth through inhibition of constitutively activated AKT and mTOR pathways." (PMID 38033496, 2023). "In summary, the abnormal activation of the PI3K/AKT/mTOR signalling pathway and the dysfunction of PIKK members in DNA damage repair are closely related to the occurrence of cancer and drug resistance during treatment." (PMID 37489050, 2023). "Brevilin A exhibits anti-cancer effects in various cancers including CRC, it induces apoptosis and autophagy via the mitochondrial pathway and PI3K/AKT/mTOR inactivation." (PMID 37062842, 2023). "The newly discovered immune response regulated by the mTOR–LTR–RIG-I axis provides various therapeutic possibilities, and LTRs were reported to be activated by genetic factors and cancer treatment." (PMID 37543704, 2023). "This was followed by mTOR/STAT3 pathway inactivation, which ultimately inhibits proliferation and induces caspase-dependent apoptosis in ovarian SKOV-3/CDDP cancer cells." (PMID 37446140, 2023). "It has been proven that ROS can inhibit mTOR or enhance AMPK signal pathways to induce autophagy in various cancer cells, impacting cancer progression." (PMID 36678588, 2023). "The mTOR signaling pathway is typically active in KIRC and promotes cancer cell proliferation and survival." (PMID 37383233, 2023). "FAK activity was reported previously to promote both mTOR and ERK signaling; moreover, accumulating evidence implicates FAK as a key upstream activator of YAP/TAZ signaling in cancer cells." (PMID 37002363, 2023). "Although hyperactive MAPK signaling has a dominant role in cancer biology, it is fine-tuned by other signaling, such as PI3K/AKT/mTOR and AMPK, during disease progression." (PMID 37174126, 2023). "Low expression of miR-1294 can promote the proliferation, apoptosis, invasion, and migration of cancer cells, and can participate in the activation of PI3K/AKT/mTOR, RAS, JAK/STAT signaling pathways, and promote the development of cancer." (PMID 37303740, 2023). "Tumor suppressor factors are negatively regulated by mTOR and AMPK, resulting in the induction of autophagy and suppression of cancer initiation." (PMID 37110415, 2023). "We amplified that TAGLN2 was positively correlated with most cancer-promoting pathways, such as glycolysis, apoptosis, hypoxia, EMT, PI3K AKT MTOR signaling, and angiogenesis." (PMID 37476180, 2023). "In contrast, the high-PCDscore group was mainly enriched in cancer- and immune-related pathways, such as WNT BETA CATANIN signaling, MTORC1 signaling, and PI3K AKT MTOR signaling." (PMID 38050240, 2023). "The activity of mTOR signaling in hepatocarcinoma cells is upregulated by OGT and O-GlcNAc to drive cancer cell proliferation." (PMID 37838167, 2023). "Numerous anti-cancer agents are known to therapeutically inhibit or activate autophagy, including those targeting the PIK3/mTOR pathway." (PMID 37046766, 2023).
cancer (continued). "We evaluated the changes in the mRNA levels of genes related to the EA-mediated inhibition of cancer cell growth and initially verified the PI3K/PTEN/AKT/mTOR pathway as the pathway by which EA inhibits HeLa cell growth." (PMID 37894909, 2023). "Persistent activation of the PI3K/AKT/mTOR/SREBP1 signaling pathway mediates adipogenesis and renders cancer cells resistant to ferroptosis in PI3K-mutant breast cancer mice." (PMID 36969840, 2023). "It was found that pathways in cancer, PI3K/AKT signaling pathway and mammalian target of rapamycin (mTOR) signaling pathway were the enriched pathways." (PMID 36776333, 2023). "One research group has shown that in four cancer cell lines of different origin, curcumin decreased glucose uptake, lactate production, and protein levels of HIF1α, PKM2, and p70S6K—the target of mTOR." (PMID 38001865, 2023). "Quercetin, in turn, stops cancer cells in the G0/G1 phase of the cell cycle, promotes apoptosis, and reduces angiogenesis by interfering with the PI3K/AKT/mTOR and STAT3 pathways." (PMID 37570691, 2023). "Recent studies have shown that this compound can inhibit PI3K/AKT/mTOR and bromodomain-containing protein 4 (BRD4) pathways in cancer cells." (PMID 37046703, 2023). "In different cancer models, Arc suppressed EGFR- and Her2-mediated signaling cascades, Akt/mTOR-, and STAT3/β-catenin-dependent pathways." (PMID 38001865, 2023). "In sum, our data indicate a new signaling cascade driven by Sema6C, via FAK kinase, leading to pERK/mTOR and YAP activation in cancer cells." (PMID 37002363, 2023). "Steroidal saponins showed anti-cancer activities on several tumor cells via different mechanisms, including downregulating MAPKs, PI3K/Akt/mTOR, MEK/ERK1/2, and Bcl-2." (PMID 36984763, 2023). "Overexpression of Akr1b1 has been observed in multiple cancer types and is thought to increase Warburg effects by triggering the AKT/mTOR signaling pathway." (PMID 36681715, 2023). "Signaling pathways, including mTOR, KRAS, STAT, and other integrin/receptor-mediated pathways like NOTCH, WNT, TGF-beta, and hedgehog signaling, play crucial roles in cancer progression." (PMID 37958444, 2023). "Mechanistically, while BRD4 inhibitors up-regulate RSK3 to activate the mTOR pathway, mTOR inhibitors block this cell survival signaling and enhance BRD4 inhibitor-mediated cancer cell apoptosis." (PMID 38135679, 2023). "Since the anti-cancer mechanisms of metformin involve direct and indirect AMPK-dependent and -independent inhibition of mammalian target of rapamycin (mTOR), we focused on the changes in mTOR and downstream ERK or S6 phosphorylation." (PMID 37835462, 2023). "Other cancers such as glioblastoma, lung, multiple myeloma and lymphomas are additionally characterized by PI3K/Akt/mTOR alterations." (PMID 37237486, 2023). "While Sema6C signaling mechanisms are poorly understood, here we show for the first time that this semaphorin controls the phosphorylation and functional activation of major intracellular signal transducers in cancer cells: FAK, ERK and mTOR kinases." (PMID 37002363, 2023). "The mTOR/P13K/AKT is involved in the progression of many cancers type and has been reported to be activated in several cancer types, including skin cancer." (PMID 37570875, 2023). "The sequence of canonical cancer pathways was also disclosed, which involved ERBB, NOTCH, IGF, cell cycle, DNA repair, PI3K-AKT, mTOR, glycolysis, and Wnt signaling." (PMID 36966136, 2023). "Due to the frequent alterations of the PI3K‐AKT‐mTOR pathway in a variety of cancers, inhibitors of the kinases PI3K, AKT and mTOR have been developed and tested in clinical trials." (PMID 37877351, 2023). "Together, these details indicate that inactivation of AKT/mTOR/p70S6K cascades and functionalization of the ERK pathway are involved in the activation of the autophagic pathway in bufalin-treated MGC803 cancer cells." (PMID 36903477, 2023).
cancer (continued). "This occurs through S-nitrosylation of key molecules involved in cancer induction, such as EGFR and TSC2, which affects the mammalian target of rapamycin (mTOR) pathway." (PMID 38248831, 2023). "The miR-143 high expression downregulates the downstream key molecules of the mTOR signaling pathway including HK2 and KRAS, thus influencing cancer cells metabolism reprogramming." (PMID 37208722, 2023). "A small-molecule Comp34 preferentially targeted TNBC and cancer stem cells and inhibited AKT1/mTOR expression by inhibition of lncRNA NUDT3-AS4, which sponged miR-99s to release the mRNA of AKT1/mTOR from miRNA-dependent decay." (PMID 37686205, 2023). "These transcripts are distinctively regulated in cellular stresses and various cancers, predominantly through modulation by the phosphoinositide 3-kinase (PI3K)–mammalian target of rapamycin (mTOR) signaling pathway." (PMID 37996663, 2023). "Thus, if drugs or procedures to increase mTOR activity in a T cell–specific manner are developed in the future, such novel treatments and PD-1 blockade may be used simultaneously to further enhance therapeutic efficacy in patients with cancer." (PMID 36378537, 2023). "Out of the 10 cancer-related pathways obtained using RPPA technology, only the PI3K/AKT, TSC/mTOR, and RTK pathways were found to have significantly lower activation levels in the LMN High group compared to the LMN Low group." (PMID 38144565, 2023). "The mTOR/PI3K/AKT pathway is an important regulatory route for controlling cell proliferation and promoting the tumorigenesis of various cancers." (PMID 37628807, 2023). "TCP1 is an oncogene in various cancers, which improves cell proliferation through the activation of the PI3K/AKT/mTOR signaling pathway." (PMID 37416927, 2023). "miR-145 has been reported to act as an important regulator of several well-documented pathways, such as the ERK/MAPK, mTOR/p70S6K1, and TGF-β pathways, which are frequently disrupted in cancer." (PMID 37373169, 2023). "The major gene targets of four core herbs, MMP9, BCL2, STAT1, and STAT3, each as a subset of pathways in cancer, were confirmed to be involved in the MAPK pathway, the mTOR pathway, and cytokine–cytokine receptor interaction." (PMID 37631075, 2023). "Pathways known to be involved in cancer stemness are the Hedgehog signaling pathway, PI3K/AKT/mTOR Complex (mTORC) pathway, and NOTCH pathway as well as Myc and NF-κB." (PMID 37958433, 2023). "TGFβ downregulates the expression of NKG2D on NK cells and CD8+ T cells in several cancer models, and has been shown to suppress IL-15 and STAT5-mediated NK cell activation through the blockade of mTOR activation." (PMID 36980629, 2023). "We also analyzed the evolutionary dynamics of six cancer pathways of two major axes: Notch/WNT/Hedgehog and AKT/mTOR/EGFR." (PMID 37174700, 2023). "Apigenin has been reported to target multiple signaling pathways, such as the PI3K/Akt/mTOR, MAPK/ERK, JAK/STAT, NF-κB, and Wnt/β-catenin pathways, involved in the development and progression of cancer." (PMID 38203418, 2023). "In these cancer cells, the level of O-GlcNAc correlates with the expression level of FASN, which is a positive regulator of mTOR signaling." (PMID 37838167, 2023). "It has been reported that the PI3K/Akt/mTOR pathway is overactivated in over 60% of patients with TNBC, eventually contributing to cancer cell proliferation, metastasis, and survival." (PMID 38067432, 2023). "According to recent studies, the activation of AKT/mTOR signaling pathway leads to radiotherapy resistance in various cancers, and many valuable inhibitors have been developed targeting AKT/mTOR, such as MK-2206, AZD5363, BI860585, GDC-0349, etc.." (PMID 37940975, 2023). "In the D5 (DAC stage), mTOR signaling (e.g., AKT2 and RPTOR) and EGFR signaling (e.g., EGFR and GSK3B) were overrepresented, implying the progression of cancer and tumor growth." (PMID 36991000, 2023).